ACLY (ATP citrate lyase)
Diseases named in the same sentence as ACLY in open-access papers (continued):
Sharing a sentence is not in itself a finding about the gene and the disease.
lymphoma (3 papers, 2020 to 2025). A malignant (clonal) proliferation of B- lymphocytes or T- lymphocytes which involves the lymph nodes, bone marrow and/or extranodal sites. "To determine whether ACLY activity is required for PD-1-deficient lymphoma cell survival, we next incubated transformed ITK–SYK+PD-1− T cells from tamoxifen-injected ITK-SYKCD4-CreERT2;Pdcd1−/− mice with an ACLY inhibitor." (PMID 37723306, 2023). "To genetically define whether ACLY is necessary for PD-1-deficient lymphoma growth in vivo, we disrupted Acly in transformed ITK–SYK+PD-1− T cells using CRISPR–Cas9-mediated gene editing and transplanted these cells into syngeneic wild-type hosts." (PMID 37723306, 2023). "We asked whether AP-1 hyperactivity in ITK–SYK+PD-1− lymphoma cells is induced by ACLY activity and subsequently inflated acetyl-CoA pools." (PMID 37723306, 2023). "On the one hand, it is unclear whether unleashed ACLY activity in PDCD1-mutant lymphomas regulates acetyl-CoA-dependent metabolic pathways apart from histone acetylation, similar to de novo generation of lipids." (PMID 37723306, 2023). "Importantly, AP-1 hyperactivation in Pdcd1-deleted lymphoma cells was critically dependent on ACLY activity." (PMID 37723306, 2023). "Conversely, pharmacological inhibition of ACLY curtails AP-1 hyperactivation and is toxic to PDCD1-mutant lymphomas." (PMID 37723306, 2023). "Consistent with published results, exogenous supplementation of acetate at physiological levels (100 μM) could not restore decreased H3K27ac signals in ACLY inhibitor-treated lymphoma cells." (PMID 37723306, 2023).
ovarian tumor (3 papers, 2016 to 2022). "ACLY knockdown reduced cell proliferation, while promoted apoptosis in ovarian tumor cells via CCND1 and CDK4 downregulations and P16 upregulation." (PMID 37303943, 2021). "CAOV3- and HeyA8-derived ovarian tumour growth was also greatly rescued by ACLY and OGDH overexpression." (PMID 27892457, 2016). "There was significant ACLY upregulation in CDDP-resistant ovarian tumor cells." (PMID 37303943, 2021). "To determine the positive correlation between USP13 and ACLY/OGDH levels in clinical ovarian tumours, we examined their levels using a tumour tissue microarray including 72 clinical ovarian tumour samples." (PMID 27892457, 2016).
Down syndrome (2 papers, 2020 to 2021). "Analogous involvement of the citrate pathway was found in Down syndrome, where hydroxycitrate—a natural ACLY inhibitor—reduced the typical prooxidant status, but the addition of malate or NADPH abolished its antioxidant effect." (PMID 34122722, 2021). "Of note, ACLY mRNA levels are increased in Behçet’s syndrome, a multisystemic inflammatory disease, and both CIC and ACLY protein levels are raised in children with Down syndrome, a genetic disorder showing some inflammatory phenotypic aspects." (PMID 33096779, 2020).
dyslipidaemia (2 papers, 2022 to 2024). "ACLY inhibitors have shown clinical efficacy in the treatment of dyslipidaemia and other cardiovascular disorders when used as monotherapy or combination therapy with other lipid-modulating drugs." (PMID 36064336, 2022). "Therefore, inhibition of ACLY can be used to improve non-alcoholic steatohepatitis (NASH), liver fibrosis and dyslipidaemia." (PMID 39595653, 2024).
HCMV infection (2 papers, 2013). "Activation of AMPK induces GLUT4 expression, and HCMV infection has been shown to activate GLUT4 independently of its normal control mechanisms, which include external glucose concentration, ATP-citrate lyase (ACL) activation, insulin stimulation, and Akt activity." (PMID 23935494, 2013).
head and neck cancer (2 papers, 2023). A primary or metastatic malignant neoplasm affecting the head and neck. "Nonetheless, there’re limited reports on the role of ACLY in head and neck cancer, warranting further in-depth investigation." (PMID 37927468, 2023). "Notably, treatment of HNSCC cells with the ACLY inhibitor BMS303141 has been demonstrated to facilitate radiosensitivity via disturbing the DNA damage repair process, implying the potential role of ACLY inhibitor as a sensitizer for head and neck cancer treatment." (PMID 37927468, 2023).
neuroblastoma (2 papers, 2020 to 2023). Neuroblastoma (NB) is the most common solid, extracranial childhood tumor. "PHPT1 also regulates ATP-citrate lyase (ACLY) activity or cell viability in neuroblastomas." (PMID 37237333, 2023). "Additionally, PHPT1 regulates ATP-citrate lyase (ACLY) activity or cell viability in neuroblastomas." (PMID 31752058, 2020).
renal carcinoma (2 papers, 2023 to 2025). A carcinoma arising from the epithelium of the renal parenchyma or the renal pelvis. "pVHL ubiquitinates PPAR-γ, inhibiting ACLY expression and lipid metabolism, which is associated with renal cancer progression." (PMID 39944823, 2025).
renal fibrosis (2 papers, 2022 to 2026). A final common manifestation of a wide variety of chronic kidney diseases characterized by glomerulosclerosis and tubulointerstitial fibrosis. "RIPK3 exacerbates renal fibrosis specifically via the PI3K/AKT-dependent activation of metabolic enzyme ATP citrate lyase (ACL)." (PMID 36361505, 2022).
type 2 diabetes (2 papers, 2019 to 2023). "Through PPI and GSEA, our study found that DHRS2, ABHD10, HADH and ACLY function together in type 2 diabetes." (PMID 31088900, 2019). "These genes, particularly ACLY, have had few researches on their effects on islet function in type 2 diabetes." (PMID 31088900, 2019). "We identified ACLY as hub gene and performed GSEA to deeply understand the molecular mechanism of ACLY in type 2 diabetes." (PMID 31088900, 2019).
age (1 paper, 2024). A temporal measurement of the time period elapsed since an identifiable point in the life cycle of an organism. "In conclusion, the identification of the chronic effects of HC and other ACLY inhibitors affecting different aspects of tissue function and organismal health provides a better understanding of aging and age‐related degeneration." (PMID 38760909, 2024).
alcoholic liver diseases (1 paper, 2021). A disorder caused by damage to the liver parenchyma due to alcohol consumption. "SREBP1 plays a critical role in alcoholic liver disease, and it could regulate the transcription of downstream signaling, such as FASN, SCD, and ACLY." (PMID 34690775, 2021).
allergic asthma (1 paper, 2024). A asthma with a basis in a pathological type I hypersensitivity reaction. "The TLR4/MyD88/TRIF/NF-κB signaling pathway and ACLY activity were inhibited in OVA-induced MH-S cells with knockdown of S100A8 or S100A9 and allergic asthma mice, suggesting that knockdown of S100A8 or S100A9 inhibits glycolysis by suppressing the TLR4/MyD88/TRIF/NF-κB signaling pathway." (PMID 38646478, 2024).
bacterial sepsis (1 paper, 2025). "Unexpectedly, Tgr5-deficient macrophages show reduced glycolysis and ATP citrate lyase expression, which cumulates in acetyl-CoA deficiency and impaired metabolic-epigenetic gene silencing, driving macrophages toward a hyperinflammatory phenotype during bacterial sepsis." (PMID 41377671, 2025).
cholangiocarcinoma (1 paper, 2024). A carcinoma that arises from the intrahepatic biliary tree (intrahepatic cholangiocarcinoma) or from the junction, or adjacent to the junction, of the right and left hepatic ducts (hilar cholangiocarcinoma). "Given this context, we propose that inhibiting ACLY might enhance ferroptosis in cholangiocarcinoma (CCA) cells, offering a potential avenue for therapeutic intervention." (PMID 39399493, 2024).
colitis (1 paper, 2021). Inflammation of the colon. "Together, these in vivo data confirm the important role of CUL3-KLHL25-mediated ACLY ubiquitination in colitis alleviation." (PMID 34491895, 2021). "Simultaneous depletion of ACLY partially rescued CUL3 deficiency-induced defects in iTreg differentiation and colitis alleviation." (PMID 34491895, 2021). "When we removed CUL3 to block ACLY degradation, iTreg differentiation and colitis alleviation by adoptive iTreg cells in mice were compromised." (PMID 34491895, 2021). "ACLY ubiquitination promotes iTreg cell generation and alleviates mouse colitis." (PMID 34491895, 2021). "Results in this work have shown that ACLY inhibition by SB204990 effectively alleviated colitis in mice, suggesting that this small-molecule inhibitor (SB204990) may have a promising role in the clinical treatment for IBD." (PMID 34491895, 2021).
cyst (1 paper, 2022). A sac-like closed membranous structure that may be empty or contain fluid or amorphous material. "We conclude that BA and ACLY inhibition inhibited cyst growth in vitro, and BA decreased ADPKD severity in vivo." (PMID 36504724, 2022). "To examine the role of ACLY more directly in governing ADPKD cyst growth in vitro, we generated stably transduced PH2 and PN24 cell lines using the pGIPZ lentiviral system to express either shRNA directed against mouse Acly (KD cells) or a non-silencing shRNA control." (PMID 36504724, 2022). "Taken altogether, these experiments further confirmed our hypothesis that BA treatment and ACLY inhibition has the promise of a therapeutic effect in vivo by inducing a significant reduction in cyst size in ADPKD in vitro 3D cell culture models." (PMID 36504724, 2022). "We hypothesized that BA could be a novel ADPKD therapy by inhibiting cyst growth, proliferation, injury, and metabolic dysregulation via ACLY inhibition and AMPK activation." (PMID 36504724, 2022). "We similarly tested whether these two ACLY inhibitors could reduce cyst area in IMCD-derived Pkd1−/− (ID1-3E5) cells grown in 3D Matrigel cultures treated with IBMX and forskolin and found that BA and SB-204990 both significantly reduced cyst size compared with vehicle (DMSO)." (PMID 36504724, 2022). "Moreover, we surmised that the higher ACLY activity in these ADPKD cell models potentially contributes to cystic growth and disease progression, and thus that targeting this enzyme for inhibition by BA in vivo may be beneficial in reducing cyst size in ADPKD mouse models." (PMID 36504724, 2022).
Dilater cardiomyopathy (1 paper, 2024). "The remaining pathways were all detected with a predominance of control proteins, such as the Citrate cycle (TCA cycle) (P-value < 0.0001; ACLY, DLST, PDHA1, PDHB), except Dilater cardiomyopathy (DCM) (P-value = 0.0006; ACTB, ADCY8, LOC396781, TPM1)." (PMID 38409238, 2024).
ductal carcinoma in situ (1 paper, 2018). "BCSCs (CD24− CD44+ ESA+) isolated from MCF10DCIS.com cells, which give rise to ductal carcinoma in situ, exhibit higher expression levels of lipogenic genes such as ATP citrate lyase (ACLY), acetyl CoA carboxylase 1 (ACC1), and FASN compared to non-stem cancer cells." (PMID 29907133, 2018).
endometriosis (1 paper, 2022). The growth of functional endometrial tissue in anatomic sites outside the uterine body. "In this study, we screened four characteristic genes of endometriosis (ACLY, PTGFR, ADH1B, and MYOM1) by using the full transcriptome sequencing data of clinical samples and public database resources." (PMID 35938015, 2022). "Hence, four genes were defined as characteristic genes for endometriosis by overlapping the genes derived from these two algorithms, including ACLY, PTGFR, ADH1B, and MYOM1." (PMID 35938015, 2022).
esophageal squamous cell carcinoma (1 paper, 2024). Esophageal squamous cell carcinoma (ESCC) is a type of esophageal carcinoma (EC) that can affect any part of the esophagus, but is usually located in the upper or middle third. "However, the roles of ACLY in oesophageal squamous cell carcinoma (ESCC) remain unclear." (PMID 38426936, 2024).
Huntington disease (1 paper, 2019). Huntington disease (HD) is a rare neurodegenerative disorder of the central nervous system characterized by unwanted choreatic movements, behavioral and psychiatric disturbances and dementia. "In the KEGG pathways enrichment analysis, we found low ACLY expressers involved in 27 downregulated pathways, including pathways linked to oxidative phosphorylation, proteasomes, Huntington’s disease and the citric acid cycle." (PMID 31077215, 2019).
hyperlipemia (1 paper, 2022). "ATP citrate lyase (ACLY) is a key enzyme in glucolipid metabolism and its aberrantly high expression is closely associated with various cancers, hyperlipemia and atherosclerotic cardiovascular diseases." (PMID 36142671, 2022).
hyperuricemia (1 paper, 2024). An abnormally high level of uric acid. "A more recent study demonstrated that EA ameliorates high fructose-induced hyperuricemia and NAFLD through activation of C1q/tumour necrosis factor-related protein (CTRP3) and inhibition of ATP citrate lyase (ACL) in male albino rats." (PMID 38671932, 2024).
Hypoglycemia (1 paper, 2026). A decreased concentration of glucose in the blood. "Hypoglycemia brought about similar (approximately 20-30%) decreases in pyruvate dehydrogenase complex (PDHC) and ATP-citrate lyase (ACLY) activities and a 65% decline in lactate dehydrogenase (LDH) activity in NCs and DCs." (PMID 42274552, 2026).
intestinal tumors (1 paper, 2024). "Even though the intestinal tumors in our mouse model had higher ACLY PSI than adjacent normal tissue, much like their human counterparts, ACLY exon 14 KO did not attenuate tumor formation or growth." (PMID 38815867, 2024).
lactic acidosis (1 paper, 2020). Metabolic acidosis characterized by the accumulation of lactate in the body. "The level of labeled acetate illustrated that acidosis, especially lactate acidosis decreased glucose-to-acetate metabolic switch in MCF-7, which may suggest that acidosis and lactic acidosis could decrease ACLY expression, while MDA-MB-231 was not sensitive to this stimulation." (PMID 33319827, 2020).
liver diseases (1 paper, 2020). "Dysregulated expression of lipogenic genes, including ATP-citrate lyase (ACLY), has been found in liver diseases associated with lipid accumulation." (PMID 32054087, 2020).
male infertility (1 paper, 2021). The inability of the male to effect fertilization of an ovum after a specified period of unprotected intercourse. "Among these genes, ATP citrate lyase (ACLY), a vital gene involved in the TCA cycle whose mRNA was hyper-methylated and down-regulated in the Fts group, has been implicated in male infertility." (PMID 34344298, 2021).
malignant mesothelioma (1 paper, 2021). A malignant neoplasm of the pleura or peritoneum, arising from mesothelial cells. "Moreover, citrate level was found depleted in malignant mesothelioma cells (compared to non-malignant cells), and microRNA-126, which suppresses tumor growth, also restored citrate level through the inhibition of ACLY and the Protein Kinase B (also named Akt), a pathway promoting ACLY activation." (PMID 34205414, 2021).
metabolism (1 paper, 2020). "ACLY has been considered an effective target for the treatment of diseases associated to disorders of lipid metabolism." (PMID 32054087, 2020).
metastatic prostate carcinoma (1 paper, 2023). A carcinoma that arises from the prostate gland and has spread to other anatomic sites. "PPARG is a classic transcription factor triggered by ligand, activating lipid signaling by upregulating acetyl-CoA carboxylase (ACC), fatty acid synthase (FASN) and ATP citrate lyase (ACLY), and promotes the metastatic prostate cancer." (PMID 37932808, 2023).
nephrolithiasis (1 paper, 2026). The presence of a calculus in the pelvis of the kidney; this is most often composed of mineral salts and proteins. "Furthermore, ACLY activity influences hypocitraturia, a key factor in nephrolithiasis, and is upregulated in polycystic kidney disease, where its inhibition attenuates cystic growth." (PMID 41958067, 2026).
oligodendroglioma (1 paper, 2014). A well-differentiated (WHO grade II), diffusely infiltrating neuroglial tumor, typically located in the cerebral hemispheres. "We next measured ACLY and pACLY levels in 1p19q co-deleted oligodendroglioma patient samples with known CIC and IDH1 status." (PMID 25277207, 2014).
osteoporosis (1 paper, 2026). A condition of reduced bone mass, with decreased cortical thickness and a decrease in the number and size of the trabeculae of cancellous bone (but normal chemical composition), resulting in increased fracture incidence. "The imbalance between osteoporosis (OP) and fracture healing is often accompanied by excessive activation of OCs, which are derived from the monocyte-macrophage system and depend on histone acetylation regulated by enzymes such as ATP-citrate lyase (ACLY)." (PMID 41522338, 2026).
psoriasis (1 paper, 2025). An autoimmune condition characterized by red, well-delineated plaques with silvery scales that are usually on the extensor surfaces and scalp. "Therefore, inhibiting ACC1 and other core enzymes of FAS, including ACLY and FASN, represents an attractive therapeutic strategy for psoriasis." (PMID 40360755, 2025).
pulmonary arterial hypertension (1 paper, 2024). Pulmonary arterial hypertension (PAH) is a group of diseases characterized by mean pulmonary artery pressure >20 mmHg and elevated pulmonary arterial resistance leading to right heart failure. "During pulmonary arterial hypertension (PAH) pathogenesis, SIRT7 upregulates AKT in a JNK-dependent manner that, in turn, activates lipogenic enzymes ATP-citrate lyase and acetyl-CoA carboxylase, promotes lipid deposition, and remodels the pulmonary vasculature in favor of PAH." (PMID 37676263, 2024).
sarcopenia (1 paper, 2025). Progressive decline in muscle mass due to aging which results in decreased functional capacity of muscles. "It has been reported that CILP2 affect sarcopenia and hypertrophic scar by antagonizing Wnt signaling pathway, and reducing the ubiquitination of ACLY, respectively." (PMID 41244802, 2025).
serous ovarian cancer (1 paper, 2015). "ACLY (ATP citrate lyase) is a crucial gene in the lipogenic pathway that is overexpressed in serous ovarian cancer." (PMID 25644622, 2015).
T cell lymphomas (1 paper, 2023). "Moreover, our data highlight the (PI3K)–AKT–mTOR–HIF1α–ACLY-axis as a genotype-specific therapeutic vulnerability in aggressive T cell lymphomas with defective PD-1 function, which should be tested in future clinical interventions." (PMID 37723306, 2023).
triple-negative breast carcinoma (1 paper, 2022). An invasive breast carcinoma which is negative for expression of estrogen receptor (ER), progesterone receptor (PR), and human epidermal growth factor receptor 2 (HER2). "Moreover, ATP citrate lyase (ACLY), a key enzyme responsible for de novo fatty acid synthesis, was considered to enhance triple-negative breast cancer (TNBC) stemness and metastasis via miR-206/ITGA2/ACLY-CCND1 signaling axis." (PMID 35852149, 2022).
Ureteral obstruction (1 paper, 2026). Obstruction of the flow of urine through the ureter. "In murine models of folic acid and unilateral ureteral obstruction, ACLY expression, acetyl-CoA levels, and H3K27ac were increased in injured kidneys." (PMID 41990244, 2026).